RN7SL213P (RNA, 7SL, cytoplasmic 213, pseudogene)
Gene: Miscellaneous RNA gene on chromosome 14 (67,751,228 to 67,751,544, reverse strand). Ensembl gene ENSG00000239820.
Homologues: Orthologues: chimpanzee Metazoa_SRP (99% identical), macaque Metazoa_SRP (94% identical). Paralogues in human: RN7SL1 (76% identical), RN7SL2 (76% identical), RN7SL122P (75% identical), RN7SL3 (75% identical), RN7SL126P (74% identical), RN7SL566P (74% identical), RN7SL127P (74% identical), RN7SL523P (74% identical), RN7SL322P (74% identical), RN7SL333P (74% identical), RN7SL357P (74% identical), RN7SL555P (74% identical), and 701 more.